BACE1 (beta-secretase 1)
Diseases named in the same sentence as BACE1 in open-access papers (continued):
Sharing a sentence is not in itself a finding about the gene and the disease.
myocardial ischemia (1 paper, 2017). A disorder of cardiac function caused by insufficient blood flow to the muscle tissue of the heart. "Although Bace1 inhibition attenuates neuroinflammation, its role in myocardial ischemia and TH-mediated cardioprotection is unknown." (PMID 28446882, 2017).
neurosyphilis (1 paper, 2022). Infection of the brain or spinal cord by Treponema pallidum. "The study found that plasma BACE1 levels were significantly correlated with CSF BACE1 levels in the neurosyphilis group." (PMID 36452956, 2022). "Interleukin, MIF, Tau protein, BACE1, sTREM2, and β2-microglobulin and metagenomic and metabolomic factors are considered to be potential markers in the CSF detection of neurosyphilis." (PMID 36452956, 2022).
Onset (1 paper, 2015). The age group in which disease manifestations appear. "It is important to note that in healthy individuals, the ∝–secretase enzyme is used to cut APP instead of BACE1, suggesting a strong correlation between elevated levels of the BACE1 and late-onset Alzheimer’s in patients." (PMID 26543800, 2015).
osteosarcoma (1 paper, 2024). A usually aggressive malignant bone-forming mesenchymal neoplasm, predominantly affecting adolescents and young adults.
ovarian failure (1 paper, 2025). "In the HIPP, protein content was not significantly different between groups when looking at total APP, sAPPα, sAPPβ, BACE1, the sAPPα/sAPPβ ratio, nor was BACE1 and ADAM10 enzyme activity affected by ovarian failure (P > 0.05)." (PMID 39711362, 2025).
overnutrition (1 paper, 2023). An imbalanced nutritional status resulting from excessive intake of nutrients. "It has been also demonstrated that overnutrition-related signals upregulate the expression of Bace1." (PMID 36672155, 2023).
pancreatitis (1 paper, 2015). Inflammation of the pancreas. "Acute experimental pancreatitis was induced by intraperitoneal injection of caerulein in homozygote Bace1-/- mice and wild type mice." (PMID 25961820, 2015). "Bace1-/- mice develop a moderate pancreatitis that is comparable in histomorphological and serological features with those seen in wild type mice." (PMID 25961820, 2015). "We demonstrate that total loss of Bace1 in mice leads to no alterations in the course of acute experimental caerulein-pancreatitis." (PMID 25961820, 2015). "In addition, elevated plasmatic lipase activity in the caerulein-group (Bace1-/- mice (3.9 ± 1.9 μkat/L) and WT mice (3.8 ± 1.9 μkat/L)) was detected after 8 hours, indicating a successful induction of pancreatitis." (PMID 25961820, 2015). "Loss of Bace1 does not alter the severity of experimental caerulein-pancreatitis in mice." (PMID 25961820, 2015). "During caerulein pancreatitis Bace2 mRNA expression was significantly reduced in both C57BL/6 and Bace1-/- mice as compared to wild-type C57BL/6 mice of the saline group." (PMID 25961820, 2015). "Bace1-/- mice and wild type controls treated with sterile saline showed no histological signs of pancreatitis (data not shown)." (PMID 25961820, 2015). "However, targeted disruption of Bace1 in mice had no influence on the development and severity of acute experimental pancreatitis on the basis of histological, immunohistochemical and serological findings." (PMID 25961820, 2015). "Thus, targeted disruption of Bace1 has no influence on the extent of inflammation in acute experimental pancreatitis compared to wild type controls." (PMID 25961820, 2015). "With our findings we can assume, that Bace1 might not be directly involved in the process of acute experimental caerulein-pancreatitis in mice." (PMID 25961820, 2015).
peripheral nerve injury (1 paper, 2021). Injury to a peripheral nerve. "A clearer picture of potential benefits of BACE1 activity in the context of peripheral nerve injury has yet to emerge." (PMID 33722254, 2021). "Cleavage of the BACE1 substrate, ST6gal-1, may provide evidence of a beneficial role of BACE1 activity following peripheral nerve injury." (PMID 33722254, 2021).
pheochromocytoma (1 paper, 2011). "Fungal endophytic extracts for BACE1 inhibitory activity and cytotoxicity against PC-12 (a rat pheochromocytoma with neuronal properties) and WRL68 (a non-tumorigenic human hepatic) were investigated." (PMID 21943123, 2011).
prostate carcinoma (1 paper, 2023). A carcinoma that arises from epithelial cells of the prostate gland. "Furthermore, to identify the molecular pathways associated with the BACE1 inhibition, the prostate cancer-specific pathway array analysis was performed in tumor tissues of both vehicle- and MK-8937 treated mice." (PMID 38201438, 2023). "In the present study, we assessed BACE1’s usefulness as a therapeutic target in prostate cancer (PCa)." (PMID 38201438, 2023). "The role of this pathway is well-established in various neurological disorders, and in the present study, we report the role of the BACE1 enzyme in prostate cancer (PCa) growth and progression." (PMID 38201438, 2023).
prostate tumors (1 paper, 2023). "Therefore, immunostaining of Aβ1-42 deposits was performed to confirm the functional activity of BACE1 in prostate tumors." (PMID 38201438, 2023).
Retinal dysplasia (1 paper, 2022). Abnormal growth and differentiation, structure and appearance of the retina present from birth. "The consequence of injecting BACE-1 inhibitor, but not vehicle, was retinal dysplasia." (PMID 35216328, 2022).
sleep disorder (1 paper, 2020). A change from the patient's baseline sleeping pattern, in the hours slept and/or an alteration/dysfunction in the stages of sleep. "Sleep disorders have been reported for other BACE1 inhibitors in other trials." (PMID 32410694, 2020).
sporadic CJD (1 paper, 2012). "In this paper, we investigated for the first time a possible association of a common synonymous BACE1 polymorphism at codon 262 (NM_012104.3:c.786G>C, rs638405) with sporadic CJD (sCJD)." (PMID 22952813, 2012).
status epilepticus (1 paper, 2012). Status epilepticus is defined as a continuous seizure lasting more than 30 min, or two or more seizures without full recovery of consciousness between any of them. "To determine whether TLE-induced BACE1 overexpression could promote amyloidogenic and p-tau pathology, we induced status epilepticus in 3×Tg-AD mice." (PMID 23155407, 2012). "Mossy fiber sprouting into the inner molecular layer was distinctly labeled by the BACE1 antibody in epileptic mice surviving 3–6 months after pilocarpine-induced status epilepticus, recapitulating the characteristic pathological pattern of aberrant axonal sprouting in TLE." (PMID 23155407, 2012).
teratocarcinoma (1 paper, 2013). A germ cell tumor characterized by the presence of an embryonal carcinoma component and a teratoma component. "The intensity of cleavage of EpCAM through BACE1 was cell line-dependent and appeared most prominent in HEK293 cells, whereas it was minor in teratocarcinoma cells, where major cleavage of EpEX was essentially metalloprotease-dependent." (PMID 24009667, 2013).
neurodegenerative disease (41 papers, 2007 to 2026). A disorder of the central nervous system characterized by gradual and progressive loss of neural tissue and neurologic function. "Knowledge of the mechanisms of anterograde transport of APP and BACE1 is also relevant for the understanding the molecular basis of dysfunctional trafficking associated with neurodegenerative diseases." (PMID 35076977, 2022). "In summary, our results show that BACE1 rs638405 is associated with an increased risk for developing PD, increasing the spectrum of neurodegenerative diseases that this variant plays a role in." (PMID 26788404, 2015). "YY1 is a ubiquitous transcription factor previously noted to regulate several genes associated with neurodegenerative diseases including BACE1 and APP, SNCA, EAAT2, MTOR and PPARGC1A." (PMID 25187168, 2014). "First, UPS impairment leads to the dysregulation of gene expression by reducing the degradation of transcriptional factors, e.g., NF-κB, HIF-1α, NFAT, etc., which contributes to the dysregulation of neurodegenerative disease-associated proteins, e.g., BACE1, RCAN1, TMP21, etc.." (PMID 31508418, 2019). "High intake of SFAs such as palmitic and stearic acid for example has been associated with increased risk for cardiovascular and neurodegenerative diseases, with evidence indicating increased tau hyperphosphorylation and increased expression of the amyloid beta generating enzyme, BACE1." (PMID 30564087, 2018). "It remains uncertain whether and how BACE1 is associated with aging or neurodegenerative disease since under our experimental conditions BACE1 mRNA levels significantly decreased during physiological aging and beside the increase in the expression of APP, they remain unchanged in AD-PBMCs." (PMID 22414021, 2012). "We then tested monoclonal Tau and BACE1 antibodies previously used in human and rodent neurodegenerative disease studies using immunohistochemistry and western blotting to validate the homology for these proteins." (PMID 38540368, 2024). "The presence of the peptide in the brain is essential, considering that the target is BACE-1 from neurons to treat a neurodegenerative disease." (PMID 37397495, 2023). "The inhibition of BACE-1 has been an important pharmacological strategy in the treatment of this neurodegenerative disease." (PMID 37175873, 2023). "Several studies have searched for a BACE-1 inhibitor to control neurodegenerative diseases, especially AD." (PMID 37397495, 2023). "β-site amyloid precursor protein (APP) lyase-1 (BACE1) is a key molecule regulating the microglial phenotype transition in neurodegenerative diseases." (PMID 37552127, 2023). "A novel 4-methylthiocoumarin derivative has been studied against acetylcholinesterase, butyrylcholinesterase, BACE1, β-amyloid aggregation, and oxidative stress involved in the pathogenesis of this neurodegenerative disease." (PMID 35956851, 2022). "The probe was successfully applied in monitoring endogenous BACE1 in vivo for the first time, indicating great potential to apply in the diagnosis of neurodegenerative disease." (PMID 36494704, 2022). "The topological analysis suggests that the amyloid-beta precursor protein (APP) was the major neighboring protein of BACE1, and its potential role in the pathogenies of neurodegenerative diseases has also been reported." (PMID 32630418, 2020). "There are many aptamer-druggable targets for the treatment of neurodegenerative diseases, such as BACE1, α-Syn, prion, and mHTT." (PMID 31766318, 2019). "miR-29a/b also target several proteins involved in neurodegenerative diseases, including BACE1/β-secretase, of which elevated levels can lead to increased amyloid β-peptides in patients with sporadic Alzheimer’s disease." (PMID 28260163, 2017).
neurodegenerative disease (continued). "Among the three tanshinones, 1 exhibited the most desirable pharmacological activities, along with the reported abilities to inhibit cholinesterases, BACE1, and Aβ aggregation, suggesting that 1 may have a promising role in neurodegenerative diseases." (PMID 34356625, 2021). "In addition, various neurodegenerative disease-associated proteins are degraded via UPS, e.g., BACE1, RCAN1, TMP21, etc.." (PMID 31508418, 2019). "Furthermore, oxidative stress increases the levels of phosphorylated tau protein, GSK3β, BACE1, and Aβ in neurodegenerative diseases." (PMID 26635562, 2015). "In conclusion, this preliminary screening of fungal endophytic extracts revealed their potential as a source of BACE1 inhibitors which could have a role in the development of drugs for treatment of neurodegenerative diseases." (PMID 21943123, 2011). "Clearly further understanding of the molecular mechanisms of BACE1 elevation during AD may accelerate the development of novel therapeutic strategies to treat this neurodegenerative disease." (PMID 19415126, 2007). "In researchon neurodegenerative diseases such as Alzheimer’s, derivativeshave been developed with multitarget activities, including the inhibitionof cholinesterases (AChE/BuChE), secretases (BACE1), and modulationof γ-secretase, in addition to showing anti-inflammatory potentialby inhibiting COX-2." (PMID 41585699, 2026). "Furthermore, we employed molecular docking and molecular dynamics studies of the phenolic compounds with the proteins AChE, BChE, and BACE-1 in order to evaluate the binding characteristics and identify potent anti-amyloid agents against the neurodegenerative diseases such as AD." (PMID 31319560, 2019). "BACE-1 is an important enzyme involved in APP processing and amyloid-peptide generation that contributes to the progression of neurodegenerative diseases." (PMID 37397495, 2023). "Hence, the BACE-1 enzyme has been found to possess an evident role in the management of enzymes disease and several studies are being conducted on natural products which help in the management of this debilitating neurodegenerative disease by acting through the BACE-1 enzyme." (PMID 35956919, 2022). "The research focus is mainly on the BACE1 gene rather than the level of BACE1 protein in the other neurodegenerative diseases such as PD." (PMID 38659704, 2024).
cancer (21 papers, 2012 to 2025). A tumor composed of atypical neoplastic, often pleomorphic cells that invade other tissues. "Metastasis, which is a primary factor in cancer progression, was significantly associated with BACE1 and LINC-PINT expression." (PMID 36087249, 2022). "In BC, low levels of BACE1 are shown to be associated with cancer development." (PMID 37511924, 2023). "Recent studies have demonstrated the association of APP and Aβ with cancer, suggesting that BACE1 may play an important role in carcinogenesis." (PMID 38201438, 2023). "Only in the last 2 years, BACE1/2 have been implicated in cancer progression." (PMID 33926496, 2021). "Here, in this study, we investigated the radiosensitization effect of BACE1 functional inhibition by gene knockdown in human cancer cells." (PMID 38248330, 2024). "To investigate this possibility, we knocked down BACE1 with siRNA in cancer cell lines, and sensitization to γ-irradiation was examined by a colony formation assay, γH2AX foci and level analysis, and flow cytometry." (PMID 38248330, 2024). "Further studies are necessary to dissect the role of BACE1 and 2 and of their targets to better characterize the mechanisms by which BACE1/2 drive cancer development and progression with the final goal to lay the foundation for future therapeutic strategies." (PMID 33926496, 2021). "All these evidences highlight the importance of BACE1/2 targeting in cancer to counteract tumor growth and progression." (PMID 33926496, 2021). "Recently, different research groups tried to address the role of BACE1 and 2 in cancer development and progression." (PMID 33926496, 2021). "We measured the biological properties, including antioxidant capacity, inhibitory activities against human BACE1, and AChE, and antiproliferative activities toward five cancer cell lines, of the 18 EBPs." (PMID 32711521, 2020). "We then extended our investigation of the roles of BACE1 in ST6Gal I-mediated migration of cancer cells by co-transfecting SW480 and CT26 cells with BACE1 and WT or L37A/K40A." (PMID 22449099, 2012). "We further analyzed the expression level of BACE1 in various cancer cell lines." (PMID 38248330, 2024). "The cancer cell lines showed diverse levels of BACE1 expression levels." (PMID 38248330, 2024). "The radiosensitization effect may be different among the cancer cells with high and low levels of BACE1." (PMID 38248330, 2024). "It has been suggested that BACE1 could alter cancer progression by changing the tumor microenvironment, activating STAT3 signaling via IL-6R, and subsequently maintaining tumor-promoting macrophages." (PMID 37511924, 2023). "Several studies have also reported the role of BACE1 and Aβ in various cancers." (PMID 38201438, 2023). "Our results suggest that BACE1 could be a candidate for radiosensitization in certain cancer cells." (PMID 38248330, 2024). "Furthermore, the physiological importance of BACE-1 in cancer progression, metastasis, and responsiveness to radiation remains largely unknown." (PMID 22449099, 2012). "We found that BACE1 could be the secretase responsible for IR-induced cleavage of ST6Gal I, and showed that BACE1 mediated cleavage of ST6Gal I decreased ST6Gal I -mediated cancer cell migration." (PMID 22449099, 2012). "Therefore, BACE1 functional inhibition may lead to selective radiosensitization in cancer cells." (PMID 38248330, 2024).
cancer (continued). "Some of the prominent genes we identified through the networks are DOK5, APP, CTNND1, STX6, STX10, STX16, BACE1, and BACE2; which, agree with the regulation of various cancers based on their co-expression patterns in GeneMANIA." (PMID 37218885, 2023). "BACE1, through degradation, can reduce ST6GAL1 enzyme in cancer cells, rendering its inhibitory role in tumour metastasis diminished." (PMID 36087249, 2022). "The two compounds were screened for biological activity in a panel of bioassays, including cytotoxicity against the cancer cell lines, the inhibition on human protein tyrosine phosphatase 1B (PTP1B), α-glucosidase, and β-secretase 1 (BACE1)." (PMID 36558971, 2022). "For example, Icariside II (ICS II), an anti-cancer natural compound extracted from Herba Epimedii Maxim, was demonstrated to inhibit Aβ production by reducing APP and BACE1 expression in APP/PS1 transgenic mice." (PMID 29358920, 2017). "Despite studies suggesting the role of BACE1 and its product, Aβ, in various cancers, these molecular players have not been well-studied in PCa." (PMID 38201438, 2023). "As expected, BACE1 expression does not correlate with the prognosis of the disease pointing out that BACE2, and not BACE1, seems to be mainly involved, directly or through its targets, in the pathogenesis and/or progression of cancer." (PMID 33926496, 2021). "Indeed, even if BACE2 seems to be the β-secretase mainly involved in cancer, the availability of BACE2 specific inhibitors is problematic due to the high grade of homology with BACE1." (PMID 33926496, 2021). "Evidence exists in other cancers demonstrating EGFR activity is needed for full activation of MEK and ERK downstream of mutant KRAS and this may be the first example of that in NSCLC, reinforcing a need to target BACE1 in this setting." (PMID 40601773, 2025).